RNU6-1141P (RNA, U6 small nuclear 1141, pseudogene)
Gene: Small nuclear RNA gene on chromosome 10 (21,661,635 to 21,661,741, reverse strand). Ensembl gene ENSG00000201390.
Homologues: Orthologues: macaque U6 (92% identical), dog U6 (82% identical). Paralogues in human: RNU6-19P (88% identical), RNU6-43P (88% identical), RNU6-1091P (86% identical), RNU6-11P (86% identical), RNU6-175P (86% identical), RNU6-23P (86% identical), RNU6-35P (86% identical), RNU6-37P (86% identical), RNU6-1243P (85% identical), RNU6-12P (85% identical), RNU6-13P (85% identical), RNU6-24P (85% identical), and 1288 more.